CLEC5A (C-type lectin domain containing 5A)
Diseases named in the same sentence as CLEC5A in open-access papers (continued):
Sharing a sentence is not in itself a finding about the gene and the disease.
COVID-19 (4 papers, 2022 to 2025). A disease caused by infection with severe acute respiratory syndrome coronavirus 2. "Our previous study also showed that CLEC5A was detected in monocytes from severe COVID-19 patients and in hamster models challenged with Delta and Omicron SARS-CoV-2 strains." (PMID 41012661, 2025). "Fully vaccinated individuals with a history of COVID-19 exhibited CLEC5A expression in immune cells, but at lower activation levels than those with severe disease." (PMID 41012661, 2025). "We found that virus-free extracellular COVID-19 EVs induced robust NET formation via Syk-coupled C-type lectin member 5A (CLEC5A) and TLR2." (PMID 35820906, 2022). "Blockade of CLEC5A inhibited COVID-19 EVs-induced NETosis, and simultaneous blockade of CLEC5A and TLR2 further suppressed SARS-CoV-2-induced NETosis in vitro." (PMID 35820906, 2022). "This study demonstrates that SARS-CoV-2-activated platelets produce EVs to enhance thromboinflammation via CLEC5A and TLR2, and highlight the importance of CLEC5A and TLR2 as therapeutic targets to reduce the risk of ARDS in COVID-19 patients." (PMID 35820906, 2022). "This work clearly demonstrates that PLT-EVs from COVID-19 patients can enhance thromboinflammation via CLEC5A and TLR2, and further shows that PLT-EVs from virus-activated act as endogenous danger signals to cause systemic inflammation." (PMID 35820906, 2022). "Our research emphasizes the importance of inflammation control in post-vaccination COVID-19 management by investigating C-type lectin mechanisms, particularly CLEC5A expression and inflammatory gene activation through in vitro, in vivo and in silico experiments." (PMID 41012661, 2025). "Our previous study with human samples revealed reduced CLEC5A expression in individuals who experienced natural SARS-CoV-2 infection after vaccination, compared to unvaccinated individuals with mild or severe COVID-19." (PMID 41012661, 2025). "In this study, we further demonstrated that COVID-19 EVs express abundant markers of activated platelets, enhance NET formation via CLEC5A and TLR2." (PMID 35820906, 2022). "Here we report that COVID-19 EVs express abundant markers of activated platelets, and induce NET formation via CLEC5A and TLR2." (PMID 35820906, 2022). "Furthermore, SARS-CoV-2 and COVID-19 EVs induced NET formation via CLEC5A and TLR2, and clec5a−/−tlr2−/− mice were resistant to SARS-CoV-2-induced lung inflammation and collagen deposition." (PMID 35820906, 2022). "We demonstrated that antagonistic mAbs against anti-CLEC5A mAb and anti-TLR2 mAb can inhibit COVID-19-EVs-induced NET formation, and generated clec5a−/−/tlr2−/− mice to confirm the critical roles of CLEC5A and TLR2 in SARS-CoV-2-induced lung inflammation in vivo." (PMID 35820906, 2022). "While the activation of a robust adaptive immune response is not new to COVID-19 mRNA vaccines, the role of CLEC5A in immunization remains unclear." (PMID 41012661, 2025). "As COVID-19 sera was reported to induce NET formation, and serum levels of platelet-derived EVs (PLT-EVs) correlated with disease severity, we asked whether COVID-19 EVs induced NET formation was via CLEC5A and TLR2." (PMID 35820906, 2022). "While EVs from healthy control were unable to induce NET formation, COVID-19 EVs induced robust NET formation, which was blocked efficiently by anti-CLEC5A mAb, but not anti-TLR2 mAb." (PMID 35820906, 2022).
glioblastoma (4 papers, 2019 to 2026). The most malignant astrocytic tumor (WHO grade IV). "Previous studies on CLEC5A are mostly related to the immune response caused by microbial viruses, and most of the studies related to tumors focus on glioblastoma, but the research in OC has been a vacancy." (PMID 34712666, 2021). "Here, we reported for the first time that CLEC5A was not only involved in the progression of glioblastoma (GBM) but also linked with clinical outcome." (PMID 30834619, 2019). "The purpose of this study is to explore the regulation of the role of CLEC5A on the proliferation, apoptosis and metastasis of glioblastoma, and to further explore the related signalling pathway associated with CLEC5A in the pathogenesis of glioblastoma." (PMID 30834619, 2019). "One of research directions is to determine the ligands and binding partners of CLEC5A especially in the context of glioblastoma pathogenesis." (PMID 30834619, 2019). "In contrast, the mice injected with U87 (CLEC5A overexpression) exhibited more metastasis, indicating the facilitating effect of CLEC5A on the metastasis of glioblastoma." (PMID 30834619, 2019). "Based on the analysis from database indicating that CLEC5A had tightly correlation with glioblastoma, we next investigate the effect of CLEC5A on glioblastoma cell proliferation." (PMID 30834619, 2019). "Next, different assays were performed to investigate the functions of CLEC5A on glioblastoma cell migration, invasion, apoptosis and cell cycle." (PMID 30834619, 2019). "We found that in CLEC5A‐low glioblastoma sub‐group, unclassified group had a significant favourable OS than the other four subtypes (P = 0.04)." (PMID 30834619, 2019). "We analysed the transcript expression of CLEC5A in glioblastoma by accessing The Cancer Genome Atlas (TCGA)." (PMID 30834619, 2019). "Both in vitro and in vivo evidences supported that CLEC5A was involved in glioblastoma pathogenesis via regulation of PI3K/Akt pathway." (PMID 30834619, 2019). "Using human malignant glioblastoma cell lines U251 and U87, which have differential expression of CLEC5A, our data demonstrated that CLEC5A expression was correlated with cell proliferation, apoptosis, migration and invasion." (PMID 30834619, 2019). "Results showed that the expression of CLEC5A mRNA in glioblastoma tissues was 3.149‐fold higher than that in normal brain tissues." (PMID 30834619, 2019). "All in all, in vivo results were consistent with in vitro data and further confirmed the role of CLEC5A during glioblastoma tumorigenesis and metastasis." (PMID 30834619, 2019). "In this study, we found that CLEC5A was highly upregulated in glioblastoma compared to normal brain tissues, which had an opposite relation with the overall patient survival." (PMID 30834619, 2019). "The data mining from GBM databases demonstrated that CLEC5A had potential correlations with glioblastoma tumorigenesis." (PMID 30834619, 2019). "In summary, different approaches had revealed that CLEC5A regulated glioblastoma cell migration, invasion, apoptosis and cell cycle." (PMID 30834619, 2019). "It was indicated that CLEC5A had the highest expression level in mesenchymal glioblastoma and lowest in unclassified subtype." (PMID 30834619, 2019). "However, no significant OS difference be observed in different subtype groups of CLEC5A‐high glioblastomas (P = 0.079)." (PMID 30834619, 2019). "In addition, to further interrogate the overall survival (OS) in different glioblastoma subtypes from TCGA‐database, Kaplan‐Meier analyses were performed in both CLEC5A‐low and CLEC5A‐high sub‐cohorts." (PMID 30834619, 2019). "All of these results concluded that CLEC5A increased glioblastoma cell proliferation, which could be blocked by PI3K/Akt inhibitor." (PMID 30834619, 2019). "Akt inhibitor or agonist could reverse the modulation effects of CLEC5A in glioblastoma." (PMID 30834619, 2019).
glioblastoma (continued). "Therefore, future studies will focus on the specific function of CLEC5A in glioblastoma pathogenesis in order to strength the hypothesis that CLEC5A serves as a therapeutic target for the treatment of glioblastoma." (PMID 30834619, 2019). "Consistent with conclusions from public database, CLEC5A mRNA expression in glioblastoma tissues was about 2‐fold higher than that in adjacent normal tissues from patients, which further supported our observation of differential expression of CLEC5A in brain glioblastoma." (PMID 30834619, 2019). "Thus, CLEC5A might serve as a potential therapeutic target in the treatment of glioblastoma in the future." (PMID 30834619, 2019). "in 2021 found that the prognosis of glioblastoma (GBM) can be determined by seven differentially expressed genes (DEGs) 47, namely CLEC5A, HOXC6, HOXA5, CCL2, GPRASP1, BSCL2, and PTX3." (PMID 39132508, 2024). "According to the regulation of CLEC5A on Akt phosphorylation in glioblastoma cell lines, we further determined whether inhibition of Akt by Akt pathway inhibitors or activation of AKT by insulin signalling agonist could reverse the effects conducted by CLEC5A shRNA knockdown or overexpression." (PMID 30834619, 2019).
myocardial infarction (4 papers, 2017 to 2025). Gross necrosis of the myocardium, as a result of interruption of the blood supply to the area, as in coronary thrombosis. "CLEC5A is strongly associated with activation of the inflammasome and pyroptotic cell death, which play vital roles in myocardial infarction." (PMID 39919333, 2025). "CLEC5A knockdown protects against cardiac dysfunction after myocardial infarction." (PMID 39919333, 2025).
gastric cancer (3 papers, 2022 to 2024). A primary or metastatic malignant neoplasm involving the stomach. "In gastric cancer, CLEC5A silencing or knockdown results in decreased cell growth, colony-formation capability, and tumor volume and weight, which is consistent with the findings in GBM." (PMID 35979347, 2022). "Similarly, high CLEC5A expression was proposed as a negative prognostic factor in patients with gastric cancer." (PMID 35252461, 2022).
influenza (3 papers, 2017). An acute viral infection of the respiratory tract, occurring in isolated cases, in epidemics, or in pandemics; it is caused by serologically different strains of viruses (influenzaviruses) designated A, B, and C, has a 3-day incubation period, and usually lasts for 3 to 10 days. "The results highlight the Syk-coupled CLEC5A signaling pathway as a potential target for immunomodulators to alleviate proinflammatory response associated with influenza immunopathogenesis." (PMID 27795434, 2017). "Our results highlight the Syk-coupled CLEC5A signaling pathway as a potential target for immunomodulators to alleviate proinflammatory responses associated with influenza immunopathogenesis." (PMID 27795434, 2017). "We further determined the impact of CLEC5A on influenza pathogenesis in CLEC5A−/− and WT mice after lethal challenge with 5 50% murine lethal doses (MLD50) (4,766 PFU/mice) of the VNHA,NA virus." (PMID 27795434, 2017). "While influenza can similarly activate CLEC5A-mediated inflammatory responses in the myeloid cells, influenza viruses predominantly replicate at the respiratory epithelium cells." (PMID 27795434, 2017). "Influenza infections in bone marrow-derived macrophages of CLEC5A−/− mice showed reduced levels of TNF-α and IP-10 but increased IFN-α compared WT mice." (PMID 27795434, 2017). "In murine BMM, reduced IP-10 but elevated IFN-α levels were observed in cells derived from the CLEC5A−/− compared to the WT mice after influenza infection." (PMID 27795434, 2017). "We observed a more prominent cytokine reduction in the mouse lungs than that observed in BMM derived from CLEC5A−/− and WT mice after influenza infection, possibly due to the mixed cell types present in the mouse lungs." (PMID 27795434, 2017). "Collectively, our results suggest that dampening CLEC5A-mediated inflammatory responses in myeloid cells reduces immunopathogenesis after influenza infections." (PMID 27795434, 2017). "Overall, these observations further support the role of CLEC5A in mediating induction of proinflammatory cytokines in human macrophages after influenza infection." (PMID 27795434, 2017). "CLEC5A−/− mice with deletion of exons 3 to 5 of the murine Clec5a genomic DNA and the genetically matched WT mice were applied to evaluate the impact of CLEC5A on influenza pathogenesis." (PMID 27795434, 2017). "We observed survival advantage in CLEC5A−/− mice after lethal influenza challenge, while a more prominent survival advantage was observed at a sublethal dose." (PMID 27795434, 2017). "This suggested that dampening CLEC5A-mediated inflammatory responses in the myeloid cells is able to alleviate influenza pathogenicity in vivo." (PMID 27795434, 2017). "CLEC5A−/− mice with reduced inflammatory responses but lung viral loads comparable to those of the WT mice were only moderately protected after lethal influenza challenge." (PMID 27795434, 2017). "Our results suggest that CLEC5A-mediated enhancement of the inflammatory response in myeloid cells contributes to influenza pathogenicity in vivo and may be considered a therapeutic target in combination with effective antivirals." (PMID 27795434, 2017). "Blocking CLEC5A-mediated signaling reduced inflammatory response in M-Mφ after influenza infection." (PMID 27795434, 2017). "With reduced cytokines but comparable viral loads in mouse lungs, the CLEC5A knockout (CLEC5A−/−) mice were protected after lethal influenza challenge compared to C57BL/6 wild-type (WT) mice, although a more prominent difference was observed when they were challenged with a lower inoculum." (PMID 27795434, 2017). "Since Syk-mediated signaling was critical for CLEC5A-induced lethal shock in mice and inflammasome activation in DV pathogenesis, we asked if Syk-mediated signaling is involved in the release of proinflammatory cytokines after influenza infection." (PMID 27795434, 2017).
influenza (continued). "We identified that CLEC5A, a C-type lectin receptor which has previously been reported to mediate flavivirus-induced inflammatory responses, enhanced induction of proinflammatory cytokines and chemokines in myeloid cells after influenza infections." (PMID 27795434, 2017). "Overall, we demonstrated that dampening the CLEC5A-mediated proinflammatory cytokine response in myeloid cells may lower the excessive inflammatory response and improve survival after influenza infections." (PMID 27795434, 2017). "However, we observed a differential IFN-α response triggered in human and murine macrophage after influenza infection, which could be due to differential cross talk between CLEC5A-mediated signaling and other signaling pathways in human and murine macrophages after influenza infection." (PMID 27795434, 2017). "This is consistent with our observation that the CLEC5A−/− BMMs secreted significantly lower levels of IP-10 but not TNF-α than the CLEC5A+ BMMs after influenza infection." (PMID 27795434, 2017). "The anti-CLEC5A blocking antibodies had no impact on influenza replication, as the M gene copies detected in the M-Mφ were comparable to those of the isotype control-treated macrophages." (PMID 27795434, 2017). "The cytokine profiles between human PBMC-derived macrophages and murine BMM after influenza infections do not match fully, which could be due to differences in CLEC5A-mediated signaling or differential cross talk with other signaling pathways in these two species." (PMID 27795434, 2017).
osteosarcoma (3 papers, 2019 to 2023). A usually aggressive malignant bone-forming mesenchymal neoplasm, predominantly affecting adolescents and young adults. "In osteosarcoma, C/EBPβ acts as a transcription factor to inhibit the proliferation of osteosarcoma cells by regulating the expression of CLEC5A." (PMID 36766839, 2023). "CEBPB can inhibit the proliferation of osteosarcoma via regulating the expression of CLEC5A." (PMID 31364785, 2019).
adult-onset Still disease (2 papers, 2020 to 2022). A rare inflammatory multisystem disorder characterized clinically by fever of unknown origin, arthralgia or arthritis, hyperleucocytosis, and typical skin rash. "We postulated a potential role of CLEC5A in the pathogenesis of adult-onset Still's disease (AOSD) and aimed to investigate CLEC5A expression and its association with activity parameters and disease course." (PMID 32377540, 2020).
autoimmune disease (2 papers, 2019 to 2022). A disorder resulting from loss of function or tissue destruction of an organ or multiple organs, arising from humoral or cellular immune responses of the individual to their own tissue constituents. "Thus, blockade of CLEC5A and TLR2 using a bi-specific anti-CLEC5A/TLR2 mAb has the potential to reduce the risk of autoimmunity post-DV infection, and have therapeutic effects in autoimmune diseases by limiting excessive NET formation and persistent inflammasome activation." (PMID 31867016, 2019).
hemorrhagic fever (2 papers, 2012 to 2017). An infectious disease caused by certain viruses or bacteria that can damage the walls of tiny blood vessels, making them leak, and can hamper the blood's ability to clot and cause severe, life-threatening illness. "CLEC5A/MDL-1, a member of the myeloid C-type lectin family expressed on macrophages and neutrophils, is critical for dengue virus (DV)-induced hemorrhagic fever and shock syndrome in Stat1−/− mice and ConA-treated wild type mice." (PMID 22536153, 2012).
Listeria monocytogenes infection (2 papers, 2017 to 2025). "We further investigated the impact of CLEC5A deficiency on systemic Listeriosis by administering a sublethal dose of L. monocytogenes to mice (1 × 105 CFU per mouse, i.v.)and monitoring bacterial load in the liver." (PMID 28824166, 2017). "Although we observed less IL-1β production in Tlr2−/− than Clec5a−/− macrophages incubated with L. monocytogenes, Tlr2−/− mice were more resistant than Clec5a−/− mice to Listeria infection." (PMID 28824166, 2017). "All these observations provide compelling evidence that that CLEC5A is a critical PRR in Listeria infection." (PMID 28824166, 2017). "Higher mortality rates in knockout mice (Clec5a−/−Tlr2−/− and Clec5a−/−) compared to WT/DNase I mice indicates that the mechanism of CLEC5A-mediated protection against Listeria infection involves both NET formation and cytotoxic effects of inflammatory monocytes and neutrophils." (PMID 28824166, 2017). "Since L. monocytogenes-mediated activation of both CLEC5A and TLR2 induces phosphorylation of Syk and p65, we investigated whether CLEC5A and TLR2 collaborate in host defense against systemic Listeriosis." (PMID 28824166, 2017).
lung fibrosis (2 papers, 2022). "Blockade of CLEC5A not only attenuates lung inflammation and epithelial damage, but also it increases the efficacy of ciprofloxacin and prevents lung fibrosis caused by P. aeruginosa." (PMID 36048544, 2022). "Moreover, the combination of anti-CLEC5A mAb with antibiotics not only reduced lung inflammation in acute pneumonia, but also prevented lung fibrosis and increased host survival rate." (PMID 36048544, 2022).
viral encephalitis (2 papers, 2012 to 2013). Encephalitis resulting from viral infection. "However, whether CLEC5A is involved in the pathogenesis of viral encephalitis has not yet been investigated." (PMID 22536153, 2012).